HLA-G (major histocompatibility complex, class I, G)
Diseases named in the same sentence as HLA-G in open-access papers (continued):
Sharing a sentence is not in itself a finding about the gene and the disease.
tumor (continued). "It is remarkable that the interaction between HLA-G and ILT2 or ILT4 in tumor cells results in tumor progression, while binding of HLA-G to ILT2 or ILT4 expressed by immune cells results in suppression of these immune cells." (PMID 33213057, 2020). "HLA-G inhibits the process in which immune cells destroy tumor cells by binding to a multitude of receptors, such as KIRs, CD8, and leukocyte immunoglobulin like receptor sub family B member 1 (LIR 1), which are expressed on the surface of immune cells." (PMID 31980023, 2020). "Soluble HLA-G (sHLA-G) has been particularly relevant in the clinical setting, correlating with allograft transplantation tolerance and tumor escape." (PMID 32708387, 2020). "A positive HLA-G expression status in tumor tissue is a promising candidate parameter to predict disease recurrence." (PMID 33425752, 2020). "HLA-G-expressing tumor cells or high levels of HLA-G in plasma have been reported in numerous types of cancers and associated with higher grade and worse prognosis." (PMID 33505397, 2020). "Overexpression of the immune checkpoint HLA-G molecule by tumor cells profoundly affects tumor-specific T cell immunity in the cancer microenvironment." (PMID 32670296, 2020). "Here we emphasize the requirement of new tool development to analyze the HLA-G expression by tumor cells, especially the generation of new anti-HLA-G monoclonal antibodies to determine the expression pattern of HLA-G isoforms expressed by tumor cells." (PMID 32922387, 2020). "In the context of cancers, different degree of inter-tumor HLA-G expression has been observed in most histological types of cancers studied, and the significance of HLA-G/ILTs signaling pathway as an immune checkpoint in cancer biology has been highlighted." (PMID 33329527, 2020). "It has been postulated that this phenomenon was associated to a deep genetic disorder and rearrangement, inducing HLA-G neo-expression in tumor cells." (PMID 32922387, 2020). "Distinct pattern and variation of HLA-G expression was also observed for each antibody for HLA-G detection among 10 randomized slides from a same tumor sample." (PMID 33329527, 2020). "Human leukocyte antigen G (HLA-G), known as a central protein in providing immune tolerance to the fetus in pregnant women, is also studied for a possible role in tumor development." (PMID 32630545, 2020). "Several preclinical studies have provided some evidence that blocking HLA-G/ILTs signaling with antibody or down-regulating HLA-G expression with RNA interference can restore function of immune cells and prevent tumor reoccurrence." (PMID 33425752, 2020). "Higher HLA-G expression is correlated with advance stage of the disease, the tumor lesion depth, the node invasion and the decrease of the survival rate." (PMID 32922387, 2020). "Despite being restrictively expressed on healthy tissues, HLA-G was reported to be neo-expressed in several pathological contexts, especially during tumor development." (PMID 32922387, 2020). "In more recent studies, miR-148a-3p was found to reduce HLA-G and PD-L1 levels; therefore, its down-regulation contributes to a immunosuppressive tumor microenvironment." (PMID 32085669, 2020). "Usually this environment is difficult to maintain ex vivo, where primary cells or cell lines loose rapidly their HLA-G expression, implying that the real expression levels of HLA-G in tumor cells are frequently underestimated." (PMID 32922387, 2020). "Since tumor cells express more HLA-G, it is expected that surgical removal of such cells will subsequently lower the expression levels of HLA-G in cancer patients." (PMID 31759373, 2019). "Immune suppression by HLA-G is crucial in terms of a healthy pregnancy, but unwanted in a cancer setting where it promotes tumor growth." (PMID 31134056, 2019).
tumor (continued). "Second, different immune cells, such as NK cells, B and T lymphocytes and DCs, can acquire HLA‐G antigens from HLA‐G+ tumor cells, which can immediately convert the effector cells into temporary regulatory cells." (PMID 31489189, 2019). "HLA-G expression in tumors was related to advanced tumor stages, poor prognosis and immune suppression." (PMID 31540045, 2019). "A few HLA‐G+ tumor cells can share and spread their HLA‐G to a larger population of HLA‐G− tumor cells, thus, conferring extra protection to the cells that originally did not express HLA‐G." (PMID 31489189, 2019). "In our study too, the expression of HLA-G was largely specific to tumor tissues and there was a predominance of soluble isoforms, particularly HLA-G7." (PMID 30859089, 2019). "Tumor and serum HLA-G expression levels have been reported to be an independent marker of poor prognosis in several tumors, including NSCLC, ovarian, breast, colorectal, esophageal, gastric, hepatocellular and endometrial cancers." (PMID 30939820, 2019). "The main factors that correlate with the embryonic mesenchymal state, tumor metastases and progression include HLA-G, HSP70, hypoxia, STAT3, CD44, SNAIL1, TWIST1, PRRX1, TGFb, WNT/bCAT, ID, and MMPs." (PMID 30899759, 2019). "A subset of HLA-G-expressing T cells have also been shown to play a role in promoting a tolerogenic tumor microenvironment." (PMID 31134056, 2019). "Within a population of HLA-G- tumor cells, few HLA-G+ cells have significant immune inhibitory effects." (PMID 30899759, 2019). "By mediating an immune-suppressive surrounding, HLA-G counteracts the anti-tumor effect of tumor-infiltrating lymphocytes (TILs)." (PMID 31013867, 2019). "Herein, we discuss the relative aspects of the intercellular transfer of HLA‐G between tumor cells and immune cells and its potential use in tumor immunology research and translational cancer therapy." (PMID 31489189, 2019). "Comparing the expression pattern with respect to membrane-bound and soluble isoforms of HLA-G in tumor tissue, we found that IL-10 and IFN-γ expressions were higher in membrane-bound isoforms." (PMID 30859089, 2019). "HLA-G, existing as either membrane-bound (mHLA-G) or soluble (sHLA-G) molecule is thought to be immunosuppressive and produced more by tumor cells." (PMID 31759373, 2019). "Tumor-mediated ectopic expression of HLA-G suppresses the function of T cells and natural killer (NK) cells and induces expansion of an immunosuppressive T cell subset." (PMID 30859089, 2019). "Soluble HLA-G levels (sHLA-G) were also frequently detected and inversely correlate to numbers of activated T cells suggesting that sHLA-G promotes tumor immune escape through activation of immune responses." (PMID 31555274, 2019). "To HLA‐G‐positive cancer cells, anticancer drugs in carriers conjugated an HLA‐G mAb can be guided and delivered precisely to kill HLA‐G‐positive tumor cells." (PMID 31489189, 2019). "The immune suppression induced by HLA‐G favors tumor cell escape from host antitumor immune responses." (PMID 31489189, 2019). "The aberrant expression of HLA-G has been considered a mechanism in a wide variety of tumours that helps the tumour cells escape immunosurveillance." (PMID 30962267, 2019). "The immune‐suppressive functions of HLA‐G in tumor immunology have been well recognised since the past three decades." (PMID 31489189, 2019). "Validation analysis indicated that HLA-C, HLA-DPA1, HLA-E, HLA-F and HLA-G were associated with HCC prognosis of overall survival (all P ≤ 0.05, elevated 0.988 and 0.997 multiples compared to non-tumor tissues, respectively)." (PMID 31602270, 2019). "Independent of the source of vesicular HLA-G, the presence of HLA-G seems to render (tumor) cells immunologically invisible by transducing inhibitory signals towards effector cells promoting cancer progression." (PMID 31382533, 2019).
tumor (continued). "On the other hand, immune cells acquiring HLA‐G from tumor cells or other immune cells by direct, multiple and/or serial patterns can turn into regulatory cells, further amplifying the tolerogenic effects of HLA‐G in tumor immune escape." (PMID 31489189, 2019). "HLA-G expression was also checked in adjacent normal tissues and only 20% of the tissues showed expression of HLA-G which indicates tumor-restricted expression of HLA-G in HNSCC." (PMID 30859089, 2019). "Considering HLA-G7 as the most frequent isoform of HLA-G expressed in tumor tissue, we stratified the samples on the basis of HLA-G7 positivity and found that expression of IFN-γ was highest in HLA-G7 expressing tumors of HNSCC." (PMID 30859089, 2019). "In this scenario, aberrant induction of HLA‐G expression in malignant cells represents one of the key factors that contributes to tumor immune escape and progression." (PMID 31489189, 2019). "HLA-Gs appear to be evolutionally and genetically linked to HSP70s: heat shock, a major inductor of HSP70.1-2 expression, and arsenite chemical shock also induce HLA-G expression in tumor cell lines." (PMID 30899759, 2019). "Herein, we found that 5 genes (Shisa3, PADI1, LRP2, ANGPTL4 and ALOX15B) were upregulated and 4 genes (CXCL9, ADAMDEC1, SCGB1A1/CC10, HLA-G) were downregulated in PR tumor tissues compared to SD tumor tissues." (PMID 31801598, 2019). "We conclude that HLA-G is expressed on tumor cells and in the tumor microenvironment in a substantial proportion of both primary and relapsed untreated EwS." (PMID 29464090, 2018). "Among these samples, different tumor areas including 3–4 zones per tumor were obtained, and HLA-G expression was evaluated with immunohistochemistry." (PMID 30319626, 2018). "In other immune cells such as T cells and monocytes, acquisition of HLA-G from tumor cells or APCs can also rapidly reverse the phenotype from effector to regulatory." (PMID 30319626, 2018). "We detected HLA-G on tumor cells as well as on infiltrating lymphocytes in a substantial proportion of about one third of EwS biopsies both at first manifestation and at relapse." (PMID 29464090, 2018). "As alluded to above, HLA-G expression has been demonstrated in cHL and its high expression in the tumor microenvironment has been correlated with an inferior response rate." (PMID 29564225, 2018). "HLA-G was found to be expressed at either low, intermediate or strong densities in 16 of the 47 treatment-naive EwS biopsies (34%), either on the tumor cells (14 of 47, 30%) and/or on infiltrating lymphocytes (8 of 47, 17%)." (PMID 29464090, 2018). "In an immunocompetent mouse model, HLA-G alone was sufficient to prevent rejection of human tumors, illustrating the potency of HLA-G in mediating tumor immune escape." (PMID 29464090, 2018). "HLA-G expression was typically focal, with varying proportions of HLA-Gpos tumor cells clustered in areas of the individual tumors." (PMID 29464090, 2018). "The complexity of these mechanisms requires to study the phenotype and function of infiltrating T cells in the presence of HLA-G in the human tumor microenvironment, e.g. of humanized mouse models." (PMID 29464090, 2018). "The inter- and intra-tumor heterogeneity of HLA-G expression can be increased by the complexity of mechanisms involved in the regulation of HLA-G expression." (PMID 30319626, 2018). "Whereas, HLA-G seems to help tumor cells to escape from immunosurveillance by directly interacting with inhibitory receptors that halt innate and adaptive immune cells, Qa-2 appears to activate NK and CD8+ CTLs to reject tumors." (PMID 30574154, 2018). "In clinical settings and pre-clinical murine models, HLA-G expression was strongly related to the capability of tumor cell invasiveness and metastasis, to advanced disease stage and poor survival in cancer patients." (PMID 30234020, 2018).
tumor (continued). "Though the functions of HLA-G were first explored in reproductive immune regulation, its pre-clinical significance in tumor biology has been intensively investigated." (PMID 30319626, 2018). "HLA-G has comprehensive suppressive functions exerted in multiple steps to impair anti-tumor immune responses by interacting with receptors expressed on immune cells." (PMID 30319626, 2018). "In six samples, HLA-G was detected both on tumor cells and on infiltrating lymphocytes, whereas HLA-G expression exclusively on lymphocytes was found in two samples." (PMID 29464090, 2018). "It is now well established that HLA-G expression in cancers is highly related to immune suppressive microenvironments, advanced tumor stage, and poor therapeutic responses and prognosis." (PMID 30319626, 2018). "In clinical settings, the relevance of HLA-G heterogeneity in therapeutic and immune responses, tumor progression and prognosis has been documented in a body of previous studies." (PMID 30319626, 2018). "The percentage of HLA-G expression in tumor cells by mAbs 4H84 and 5A6G7 were compared, and the difference of the HLA-G expression (ΔHLA-G) was obtained by the percentage of HLA-G expression detected with HLA-G mAb 4H84 subtracted that with mAb 5A6G7." (PMID 30234020, 2018). "We conclude that EwS cells respond to tumor-infiltrating T cells by upregulation of HLA-G, a candidate mediator of local immune escape." (PMID 29464090, 2018). "In long-term established GBM cell lines, HLA-G was reported expressed on few tumor cells, where inhibitory signals were directed against CD8+ and CD4+ T cells but not NK cells." (PMID 29967607, 2018). "Immune cells such as activated NK cells, T cells and monocytes can rapidly acquire membrane fragments containing functional HLA-G from other cells (i.e., HLA-G+ immune or tumor cells) in their vicinity by the process of trogocytosis." (PMID 30319626, 2018). "Important insights are likely to be gained by studying the functional effects of HLA-G expressed by tumor cells on the infiltrating lymphocytes." (PMID 29464090, 2018). "In vitro, HLA-G expressed on tumor cells or soluble HLA-G inhibits antitumor NK cell and T cell responses." (PMID 29464090, 2018). "In the context of heterogeneity of HLA-G expression in cancers, the degree of HLA-G expression and the isoform profiles vary dramatically among tumor types and patients, within tumors of the same type, and between the primary tumor and metastases." (PMID 30319626, 2018). "The immunosuppressive effect of iron and HLA-G in the tumor microenvironment has been neglected and ignored as therapeutic targets." (PMID 30400822, 2018). "HLA-G, which induces immune tolerance and mediates tumor escape, is a biomarker for malignancies comparable to other immune checkpoint molecules." (PMID 29632535, 2018). "This suggests that HLA-G is upregulated in EwS as a consequence of stimulation with inflammatory cytokines released by immune effector cells within the tumor microenvironment." (PMID 29464090, 2018). "Because of these functions, neoexpression of the HLA-G molecule on tumors favors carcinogenesis and tumor progression." (PMID 30319626, 2018). "In a mouse model, EwS xenografts after adoptive therapy with tumor antigen-specific CAR T cells strongly expressed HLA-G whereas untreated control tumors were HLA-Gneg." (PMID 29464090, 2018). "From these studies, a strong relationship of HLA-G expression with tumor progression and patient outcomes has been established." (PMID 30319626, 2018). "There is substantial evidence that HLA-G can contribute to tumor immune evasion: HLA-G expression on tumor cells or secretion by bystander cells was found in various cancers and in some of these was associated with poor outcome." (PMID 29464090, 2018). "They showed that it is the tumor itself which stimulates the expression of HLA-G/sHLA-G on both cancer cells and infiltrating immune cells, especially CD68+ macrophages and CD8+ T cells." (PMID 28376925, 2017).
tumor (continued). "Our results reveal a highly heterogeneous expression of HLA‐G among tumors, among distinct tumor areas of the same tumor, and in subcellular location of HLA‐G‐expressing tumor cells." (PMID 28815885, 2017). "A high frequency of tumor cell HLA-G expression and/or increased sHLA-G levels has been found in various body fluids in a variety of cancers." (PMID 28415627, 2017). "HLA-G expression was observed in sources such as on the tumor cell, secreted, or in tumor-derived exosomes." (PMID 28415627, 2017). "Several studies have reported the role of HLA-G as a molecule involved in immune tolerance, and the expression of HLA-G has been reported on both tumor cells and myeloid cells in the tumor microenvironment." (PMID 28052009, 2017). "In HLA-G+ tumor cells, the amount of HLA-G transcripts was reduced (FON, JEG-3), while in HLA-G− tumor cells, the HLA-G transcription was positively induced (1074mel, M8, U251MG)." (PMID 28781970, 2017). "Among various factors of host immune contexture in tumor immunology, induction of an immunotolerant HLA-G expression by tumor cells has been observed in numerous tumoral tissues." (PMID 29296176, 2017). "In order to consider HLA‐G as a potential target for cancer therapy, we ought to precisely determine how prevalent the expression of HLA‐G is in tumor cells derived from patients with ccRCC." (PMID 28815885, 2017). "In clinical settings and animal models, earlier studies have demonstrated the aberrant neoexpressed HLA-G in various types of cancers was related to advanced tumor grade, more aggressive behavior and worse disease outcome." (PMID 29296176, 2017). "The human leukocyte antigen-G (HLA-G) is considered an immune checkpoint molecule involved in tumor immune evasion." (PMID 28781970, 2017). "We found that the expression of HLA‐G is highly variable among tumors and distinct areas of the same tumor, testifying a marked inter‐ and intratumor heterogeneity." (PMID 28815885, 2017). "Conversely, PET-negative patients showed higher HLA-G protein expression levels on tumor cells (50% of cases) suggesting that HLA-G protein expression inhibited tumor progression." (PMID 29285306, 2017). "Differences in basal HLA-G expression described in human cell lines here studied were consistent with data reported in TCGA datasets Xena Browser for different types of tumor." (PMID 28781970, 2017). "HLA-G expression can be modulated by epigenetic and tumor microenvironmental factors and induced in the presence of hypoxia and/or hypoxia-mimicking conditions." (PMID 28781970, 2017). "Even though all the ccRCC tumors examined expressed HLA‐G in at least a small region of the tumor, as shown by the immunohistochemical analysis, largely dissimilar profiles were revealed." (PMID 28815885, 2017). "In two other tumors (patients 4 and 5), the expression of HLA‐G evaluated by 4H84 antibody was noted in small microscopic areas of only one tumor region." (PMID 28815885, 2017). "Herein, HLA-G status and clinical parameters such as tumor histological type, patient sex, age, TNM categories, and clinical disease stage to the clinical outcome of CRC patients was evaluated." (PMID 29296176, 2017). "HLA-G is also expressed by immune cells in the tumor microenvironment by trogocitosis, thereby restricting their local proliferation and cytotoxicity." (PMID 29285306, 2017). "Conversely, HLA-G+ tumor cells in the presence of hypoxia reduced HLA-G transcriptional activity and protein expression." (PMID 28781970, 2017). "The role of HLA‐G as an immune checkpoint allowing tumor escape has been demonstrated in murine models." (PMID 28815885, 2017). "We observed opposite effects on HLA-G transcriptional activity when different tumor cellular types were exposed to hypoxia stress in comparison with normoxia conditions." (PMID 28781970, 2017). "Nevertheless, HLA-G participates in the tumor escape phenomenon because its expression can be induced in pathological conditions, like cancer." (PMID 28653974, 2017).